CXCR4 (C-X-C motif chemokine receptor 4)
Diseases named in the same sentence as CXCR4 in open-access papers (continued):
Sharing a sentence is not in itself a finding about the gene and the disease.
glioma (continued). "However, inhibiting CXCR4 in LN229 and LN308 glioma cells that were knocked down for CXCR7 expression did not further reduce levels of SDF-1α-induced phosphorylation of ERK1/2 and Akt." (PMID 23865743, 2013). "However, inhibiting CXCR4 in LN229 and LN308 glioma cells that were knocked down for CXCR7 expression did not further reduce migration towards SDF-1α." (PMID 23865743, 2013). "Similar to normal NSCs, CD133 positive cancer stem cells showed 337.8 times increase on the expression levels of CXCR4 than did CD133 negative cells, which suggests CD133 positive cancer stem cells have higher capability of migration and may play an important role in glioma invasion." (PMID 17140455, 2006).
multiple myeloma (189 papers, 2008 to 2026). "CXCR4 is overexpressed in extramedullary myeloma cells and associated with the poor prognosis of extramedullary myeloma patients." (PMID 38244066, 2024). "The SDF-1/CXCR4 axis has been implicated in the expansion and homing of myeloma cells since the inhibition of CXCR4 reduces MM homing." (PMID 34503111, 2021). "Notably, a prior study showed the combination of CBD and THC was required to inhibit expression of CXCR4 that was associated with anti-migratory effects in multiple myeloma cells." (PMID 35954477, 2022). "The SDF-1α/CXCR4 axis plays a pivotal role in the major physiological processes associated with tumor proliferation, survival, invasion, dissemination, and drug resistance in myeloma cells." (PMID 33918655, 2021). "In multiple myeloma, CXCR4 expression is associated to disease progression and poor prognosis." (PMID 31024917, 2019). "In addition, mutations in K-Ras and difference in chemokine receptor profiles including functionally intact CXCR4 have been linked to transitioning myeloma cells from intramedullary to extramedullary sites." (PMID 25200389, 2014). "Similarly, CXCR4 has also been implicated in the bone marrow specific homing capacities of multiple myeloma cells." (PMID 25272036, 2014). "As CXCR4 expression regulates myeloma cell homing and has very recently been linked to MM prognosis, this marker might further be useful for discriminating intra- and extramedullary MM lesions." (PMID 24376850, 2013). "MIF interacts with CD74 and CXCR4 on myeloma cells to promote their proliferation, survival, and immune evasion, and also supports the inflammatory environment in the bone marrow to promote tumor progression and immune suppression." (PMID 40406148, 2025). "Myeloma cells highly express CXCR4, a chemokine receptor that interacts with CXCL12, which in turn is highly expressed in the BM microenvironment and functions canonically to support quiescence and BM retention of hematopoietic stem cells (HSCs)." (PMID 40136386, 2025). "Extramedullary myeloma cells generally downregulate chemokine receptors (e.g., CXCR4, CCR1, CCR2) and adhesion molecules (e.g., CD56, CD177, VLA-4), while upregulating migration molecules (e.g., CD44, CD81, nestin)." (PMID 40136386, 2025). "The myeloma cells downregulate the surface expression of CXCR4 and instead start expressing another chemokine receptor, i.e., CCR1, which is known to enhance the egress of tumor cells from BM." (PMID 40296907, 2025). "In MM, myeloma cells utilize CXCR4 to interact with SDF-1a, resulting in the adhesion of myeloma cells to BMSCs and endothelial cells." (PMID 39087026, 2024). "At that time, plerixafor, a small-molecule bicyclam CXCR4 antagonist, was the only CXCR4 inhibitor approved by the FDA in association with G-CSF for autologous stem cell mobilization in patients with non-Hodgkin’s lymphoma and multiple myeloma (MM)." (PMID 39199390, 2024). "Here, we provide multiple lines of evidence that demonstrate the enhanced anti-myeloma effects of CXCR4 co-modified BCMA CAR-NK cells in a chemokine-independent manner." (PMID 38979422, 2024). "BM-CAFs differentiation from BM-MSCs was also shown to be dependent on SDF-CXCR4 pathway in multiple myeloma (MM), while CXCR4 inhibitors (e.g., BL-8040) resulted in CAFs removal with promising clinical responses." (PMID 39555055, 2024). "miRNA-1246 can suppress the proliferation and migration of renal cell carcinoma through targeting CXCR4 and has potential as a circulating biomarker for multiple myeloma." (PMID 37373422, 2023). "FDA-approved in 2008, and EMA-approved one year later, plerixafor is a CXCR4 antagonist indicated for the treatment of patients with lymphoma or multiple myeloma." (PMID 37513979, 2023).
multiple myeloma (continued). "Elevated serum levels of CXCL12 were found to be associated with increased osteoclast formation and bone loss in myeloma patients, and that targeted disruption of the CXCL12/CXCR4 axis inhibited osteolysis in a murine model of myeloma-associated bone loss." (PMID 37240298, 2023). "ChIP-on-chip data revealed that heparanase bound to regulatory regions of myeloma-related genes (i.e., CXCL12), encodes for SDF-1, CXCR4, CXCL2, CXCR3, CCL27, CX3CL1, and LCN2." (PMID 36980254, 2023). "In mice, treatment with CXCR4 antagonist mobilized multiple myeloma cells from the bone marrow and induced cancer cell death." (PMID 37025604, 2023). "In particular, the inhibition of CXCR4 disrupts MM cell adhesion to BM MSC mobilizing myeloma PCs into circulation and increasing BTZ-induced apoptosis in vivo." (PMID 35064098, 2022). "The correlation between CXCR4 expression and the percentage of mitochondria uptake in HMCLs was also confirmed in primary myeloma PCs." (PMID 35064098, 2022). "In this regard, hypoxia has been shown to reduce CD138 and CXCR4 expression driving myeloma cells into an immature/stem-cell like state with enhanced properties for dissemination." (PMID 35847862, 2022). "[68Ga]Ga-PentixaFor has been utilized for CXCR4-directed molecular imaging of patients with multiple myeloma or lymphoma, but also in various solid tumors." (PMID 35312939, 2022). "CXCL12 is the ligand of CXCR4 and mediates the homing mechanisms of both healthy and myeloma PCs into the BM." (PMID 35064098, 2022). "CXCR4 inhibition enhances myeloma PCs sensitivity to therapeutic agents, including BTZ, through the disruption of their interaction with BM microenvironment." (PMID 35064098, 2022). "A first in human study explored 177Lu- and 90Y-labeled pentixather for the treatment of relapsed multiple myeloma and showed partial and complete response to CXCR4-directed treatment." (PMID 34976584, 2022). "CXCR4-directed molecular imaging has been applied in various clinical scenarios, including multiple myeloma (MM), lymphoma, and also in solid tumors." (PMID 35312939, 2022). "S1PR1 depleted myeloma cells retained full CXCL12 responsiveness while CXCR4 depleted myeloma cells were unable to induce CXCL12-stimulated cell adhesion or transendothelial migration after S1P stimulation." (PMID 35756630, 2022). "CXCL12 and its receptor CXCR4 represent a critical communication axis between MSCs and tumor PCs to promote the expansion and colonization of myeloma PCs in the BM." (PMID 35064098, 2022). "For example, we have recently employed this platform to conduct successful loss-of-adhesion CRISPR screens for integrin α4β1-mediated adhesion of multiple myeloma cells to VCAM-1 upon stimulation of the chemokine receptor CXCR4 with the chemokine CXCL12." (PMID 35440579, 2022). "As mobilization of hematopoietic stem cells depends on CXCR4, inhibition of CXCR4 makes multiple myeloma cells vulnerable to chemotherapy by disintegrating adhesion of myeloma cells to the stromal cells in the bone marrow." (PMID 35505363, 2022). "The resulting CX43/CXCL12/CXCR4 interplay enhances mitochondrial trafficking from MSCs to myeloma PCs and can protect cancer cells against anti-myeloma agents." (PMID 35064098, 2022). "Reduced CXCR4, as a homing receptor for normal and malignant plasma cells in the BM, was detected in myeloma patients undergoing bortezomib-treatment." (PMID 35847862, 2022). "The C-X-C chemokine receptor type 4 (CXCR4) is a pleiotropic chemokine receptor that is expressed in not only normal hematopoietic cells but also multiple myeloma cells." (PMID 33918655, 2021). "Plerixafor (drug target: CXCR4) is a drug now used in cancer (lymphoma and multiple myeloma) after stem cell transplantation to initiate migration of stem cells in the bloodstream." (PMID 34108969, 2021). "In multiple myeloma cells, chronic hypoxia increases CXCR4 expression in a process dependent on HIF-1." (PMID 33467722, 2021).
multiple myeloma (continued). "These Jagged ligands secrete higher levels of SDF-1α in the BM microenvironment, increasing CXCR4 activation in myeloma cells." (PMID 33918655, 2021). "The SDF-1α/CXCR4 axis plays crucial roles in proliferation, survival, invasion, dissemination, and drug resistance in multiple myeloma." (PMID 33918655, 2021). "Interaction of myeloma cells and bone marrow stromal cells (BMSCs) upregulates the production of C-X-C motif chemokine ligand 12 (CXCL12), leading to increased recruitment of human monocytes expressing C-X-C motif chemokine receptor 4 (CXCR4) to myeloma TME." (PMID 34359674, 2021). "CXCR4 overexpression has been reported for multiple human tumor types, ranging from hematologic malignancies (e.g., multiple myeloma) to solid tumors, including breast, prostate, lung and colorectal cancer." (PMID 34683912, 2021). "Blockage of CXCR4 largely inhibits the recruitment of monocytes to myeloma-derived medium, indicating that circulating monocytes serve as the main source of TAMs." (PMID 34359674, 2021). "Extensive basic, translational, and clinical research has uncovered the pivotal role of the SDF-1α/CXCR4 pathway in myeloma biology." (PMID 33918655, 2021). "Others have provided evidence that CXCR4 inhibition prevented homing of multiple myeloma cells to the bone marrow compartment." (PMID 35070954, 2021). "This review summarizes the pleiotropic role of the SDF-1α/CXCR4 axis in multiple myeloma and discusses the future perspective in the SDF-1α/CXCR4 axis-targeted therapies in multiple myeloma." (PMID 33918655, 2021). "In agreement, Notch inhibition effectively prevents multiple myeloma cell migration by reducing CXCR4 expression at the transcriptional level." (PMID 31616059, 2020). "Although 68Ga-pentixafor and 68Ga-NOTA-NFB have been shown to effectively image CXCR4 expression in myeloma and other systemic malignancies, imaging CXCR4 expression in brain tumors with these ligands has been more limited." (PMID 32239371, 2020). "Ulocuplumab (BMS-936564) is a mAb against CXCR4, and is currently in phase Ib/II study to determine its safety and tolerability for patients with relapsed/refractory multiple myeloma." (PMID 33392074, 2020). "A CXCR4 inhibitor was previously approved to mobilize hematopoietic cells for transplantation in patients with multiple myeloma and non-Hodgkin’s lymphoma." (PMID 33324425, 2020). "The first clinical application of [68Ga]pentixafor PET has been carried out in patients with non-Hodgkin lymphoma and multiple myeloma, which confirmed the CXCR4 expression in these lymphoproliferative diseases as a proof-of-concept." (PMID 32757068, 2020). "In this model intravenous injection of CXCR4-over-expressing myeloma cells into NSG mice results in preferential BM homing and development of a lethal disease resembling human MM." (PMID 33239060, 2020). "This highly specific CXCR4 inhibitor was approved more than a decade ago for treatment of multiple myeloma and non-Hodgkin’s lymphomas." (PMID 33096815, 2020). "Previous work reported that anti-Notch treatment effectively prevents multiple myeloma cell migration by reducing CXCR4 expression at transcriptional level." (PMID 31616059, 2020). "Multiple myeloma cells recruit tumor-supportive macrophages through the CXCL12/CXCR4 axis and promote their polarization toward M2 phenotype." (PMID 30678736, 2019). "Lipid tracers, such as Choline or acetate, and some peptide tracers, such as Ga-Pentixafor, that targets CXCR4 (chemokine receptor-4, which is often expressed with high density by myeloma cells), are other promising PET ligands." (PMID 31024917, 2019). "Studies have identified this CD138- stem cell population express stromal cell-derived factor-1 (SDF-1), which regulates homing of multiple myeloma cells to the bone marrow, and its receptor C-X-C motif chemokine receptor 4 (CXCR4)." (PMID 31330786, 2019).
multiple myeloma (continued). "Mounting evidence suggests that the interaction between SDF-1 and CXCR4 mediates the trafficking of multiple myeloma cells in vivo." (PMID 31428156, 2019). "Plerixafor, a small-molecule antagonist of CXCR4, is widely used to mobilize hematopoietic stem cells for autologous transplantation in non-Hodgkin's lymphoma and multiple myeloma." (PMID 31428099, 2019). "Ulocuplumab, a monoclonal anti-CXCL4 antibody, as well as neutralization of SDF1 by Olaptesed-pegol (PEGylated mirror-image l-oligonucleotide), inhibit myeloma cell dissemination and suppress the CXCR4-driven EMT-like." (PMID 30002349, 2018). "CXCR4/CXCL12 blockade results in a decreased tumor cell proliferation and survival and, importantly, in the loss of myeloma cells ability to colonize the BM in vivo." (PMID 30154786, 2018). "In summary, we can conclude that CSL not only inhibits migration and invasion of myeloma cells but also can downregulate the expression of CXCR4 and MMP-9 proteins in vitro." (PMID 29773987, 2018). "In acute lymphoblastic leukemia, Notch1 regulates cell proliferation and migration through CCR5 and CCR9, and in multiple myeloma Notch regulates CXCR4." (PMID 28137279, 2017). "In multiple myeloma, the anti-CXCR4 mAb ulocuplumab was recently shown to inhibit the malignant plasma cell dissemination by suppressing the EMT-like phenotype, and similar effects cannot be excluded in NETs." (PMID 28186979, 2017). "Conversely, disruption of the CXCL12/CXCR4 interaction has been shown to promote hematopoietic stem cell mobilization, promoting immunologic response of patients with non-Hodgkin lymphoma and multiple myeloma." (PMID 28055968, 2017). "Chemokine gradients are of central importance and there are data showing the importance of an upregulated CXCR4/CXCR7/CXCL12 axis in driving recruitment of tumour cells into the bone marrow in patients with multiple myeloma." (PMID 28389623, 2017). "Considering the special inhibiting effects to SDF-1/CXCR4 signaling pathway in MM, Thal indirectly inhibits the proliferation of myeloma cells by regulating the SDF-1-trigged stiffness of BMSC and further decreases the secretion of TGFβ from BMSC." (PMID 28032590, 2017). "The studies from our groups and others have found that SDF-1α enhances the rigidity of BMSCs through its receptor CXCR4, and provides a proper environment for myeloma cell proliferation and migration." (PMID 28032590, 2017). "In our previous studies, we have demonstrated that SDF-1α secreted by myeloma cells regulated the rigidity of BMSCs through binding to its receptor CXCR4, thereby, provided a proper environment for cell attachment, growth and migration." (PMID 28032590, 2017). "In our 3D model, we observed significantly higher expression of CXCL12 on myeloma derived-MSCs and upregulated CXCR-4 expression on plasma cells, as well as significant production of sTie-2 receptor and SCF, reflecting the MM niche." (PMID 27764795, 2016). "In contrast, targeting chemokine/receptor crosstalk is feasible and therapeutically relevant, as has been shown e.g. for CXCL12/CXCR4 also in myeloma." (PMID 27732933, 2016). "AMD3100, also named Plerixafor, is an antagonist of CXCR4 which is clinically used to treat non-Hodgkin's lymphoma and multiple myeloma." (PMID 27191997, 2016). "Our findings identify the CXCR4 PET tracer Pentixafor as a novel tool for in vivo imaging of multiple myeloma." (PMID 25736399, 2015). "Here, we provide the first evaluation of in vivo CXCR4 imaging in a series of patients with a particular cancer of the lymphoid system, multiple myeloma, using the CXCR4-specific PET tracer Pentixafor in comparison with the clinically established tracer FDG." (PMID 25736399, 2015). "We identify myeloma manifestations that are positive for CXCR4 uptake and establish the use of an in vivo biomarker imaging technique for future therapeutic/theranostic purposes." (PMID 25736399, 2015).